STS (steroid sulfatase)
Diseases named in the same sentence as STS in open-access papers (continued):
Sharing a sentence is not in itself a finding about the gene and the disease.
cholesteatoma (1 paper, 2014). A pathologic process characterized by the proliferation of keratinizing squamous epithelium resulting in the accumulation of keratin and cells in the middle ear and/or mastoid. "In the present study, around 30–40 fold higher levels of STS were found in cholesteatoma compared to the tympanic membrane and EACS, whereas a counter-acting enzyme Sulfotransferase 1A1 (SULT1A1) was down-regulated to the same degree, perhaps indicating activation and a resulting over-desquamation." (PMID 25093596, 2014).
coloboma (1 paper, 2024). An abnormality in which a part of a structure in one or both eyes is missing. "Various models include: dopamine transporter (DAT) knockout mice, spontaneously hypertensive rats (SHR), steroid sulfatase, coloboma mice, and alpha-synuclein-lacking mice." (PMID 38605002, 2024). "Additional genetic variations are present in other models (dopamine transporter gene knockout mice, coloboma mice, Naples hyperexcitable rats, steroid sulfatase, alpha-synuclein-lacking mice, and neonatal lesioning of dopaminergic neurons with 6-hydroxydopamine)." (PMID 38605002, 2024).
diabetes (1 paper, 2015). "In addition to its inflammation-mediated effects, carrageenan exposure may contribute to the manifestations of diabetes through increases in cholesterol sulfate, arising from its mimicry of GAGs and inhibition of sulfatase enzymes, including steroid sulfatase." (PMID 25883986, 2015).
epilepsy (1 paper, 2022). A brain disorder characterized by episodes of abnormally increased neuronal discharge resulting in transient episodes of sensory or motor neurological dysfunction, or psychic dysfunction. "STS deficiency appears the prime candidate mechanism for epilepsy predisposition given the STS axis' role in modulation of relevant neurotransmitter receptors, and that a potentially‐pathogenic STS point mutation has been observed in two brothers with epilepsy." (PMID 36479267, 2022).
joint diseases (1 paper, 2022). "Together with previous data, our results suggest that further research into androgen metabolism and, specifically, into modifying steroid sulfatase activity could provide a promising target for therapeutic intervention in joint diseases." (PMID 35041143, 2022).
Lipedema (1 paper, 2024). Disorder of adipose tissue characterized by symmetric and bilateral enlargement of the lower extremities due to abnormal deposition of subcutaneous fat often in obese women. "E2 treatment significantly increased the gene expression of LIPE (3-fold) and STS (1.5-fold) in HD-treated lipedema cells compared to untreated cells." (PMID 38791004, 2024).
lipid metabolism disorder (1 paper, 2017). "Therefore, we propose that STS deficiency may lead to lysosomal dysfunction and lipid metabolism disorder, thus leading to accumulation of undigested substances in the intracellular and extracellular compartments of keratocytes." (PMID 28302098, 2017).
lung carcinoma (1 paper, 2022). "Likewise, results obtained with other STs inhibitors (SsaI and AL10) showed that inhibition of α2,3-sialylation impaired cell motility, adhesion, and migration through ECM components and cell invasion in ovarian and lung cancer cells." (PMID 36551619, 2022).
metabolic syndrome (1 paper, 2015). A cluster of metabolic risk factors for CARDIOVASCULAR DISEASES and TYPE 2 DIABETES MELLITUS. "This suggests that SULT1E1 and STS activities are important in energy homeostasis and that up-regulation of STS and thus an increased synthesis of estrogens may be a hepatic defensive response against the metabolic syndrome." (PMID 26213785, 2015).
metastatic cancer (1 paper, 2021). A carcinoma which has spread from the original site of growth to another anatomic site. "Similarly as shown here for KLE, patients with metastatic cancer probably had low levels of STS in cancer tissue, and varied STS levels in other tissues." (PMID 34805270, 2021).
myeloma (1 paper, 2024). "Thus, losing the STS gene in hematopoietic cells, may decrease the production of estrogen in the bone marrow and thus slow the progression of myeloma." (PMID 39223296, 2024).
ovarian tumors (1 paper, 2021). "The aim of this study was to evaluate the expression of the steroid sulfatase (STS) in 154 samples of primary ovarian tumors." (PMID 34321053, 2021). "Further studies are needed in order to demonstrate that survival of patients could be affected by the expression of STS in ovarian tumors." (PMID 34321053, 2021). "High level of sulfated DHEA has been shown in the plasma of pre and postmenopausal women as well as STS, 3β-HSD and 17β-HSD1 have been described in ovarian tumors, suggesting that active androgens acting via their receptor can promote carcinogenesis." (PMID 34321053, 2021).
protein (1 paper, 2022). "Loss of function of the C. elegans sul-2 gene (steroid sulfatase, STS) increased the concentration of sulfated steroid hormones, as well as longevity, and improved the phenotype in several C. elegans models of protein aggregation diseases." (PMID 35203497, 2022).
Sjögren's syndrome (1 paper, 2016). "Both steroid sulfatase and sulfotransferase are weak and deranged in the salivary glands in association with Sjögren's syndrome." (PMID 27773962, 2016).
urinary bladder carcinoma (1 paper, 2021). "Moreover, not only ERs but also estrogen-related enzymes, such as aromatase, steroid sulfatase (STS), and estrogen sulfotransferase (EST), have been reported in the biological/clinical behavior of various hormone-dependent carcinomas but not studied in urinary bladder carcinoma." (PMID 34257538, 2021).
cancer (29 papers, 2009 to 2025). A tumor composed of atypical neoplastic, often pleomorphic cells that invade other tissues. "Since SULTs can activate procarcinogens to reactive electrophiles, enzymes such as the steroid sulfatase and estrogen SULTs have been implicated in human carcinomas." (PMID 25802476, 2015). "The inhibition of STS may effectively reduce the availability of active hormones for cancer cells, causing a positive therapeutic effect." (PMID 32363947, 2020). "Additionally, it is well known that the STS gene encodes a key and rate-limiting enzyme to produce backbone stilbene, resveratrol, which potentiates the anti-tumor effects of different cancer therapies." (PMID 26973657, 2016). "One potential mechanism is that advanced cancer cells can alter their metabolism to overcome therapeutic attack through steroid sulfatase activity, a key enzyme of the steroid hormone metabolic pathway." (PMID 40563609, 2025). "Compounds of type 3a-3e were early used for the treatment of hormone-dependent breast cancer since they lead to a reduction of estrogenic steroids, responsible for the growth and development of this type of cancer, via the steroid sulfatase (STS) pathway." (PMID 39963267, 2025). "Given that STS is critical to androgen production and plays a role in the AR signaling pathway, it is likely that STS overexpression results in enhanced AR transcriptional activity, mediating metabolic reprogramming in cancer cells." (PMID 40563609, 2025). "Irosustat and STX140 are sulfamate derivatives that have been reported as antiproliferative agents by inhibiting steroid sulfatase with demonstrable activity against cancer cells." (PMID 36978428, 2023). "Nowadays, STS has been considered as an attractive molecular target for the development of hormone-dependent cancer therapies, and therefore, the synthesis of new, efficient, selective STS inhibitors is of particular importance for modern medicinal chemistry." (PMID 33322953, 2021). "We also found that STS expression in both HeLa and PC-3 cells rendered them to become highly invasive and STX-64 was able to prevent STS-mediated cancer cell invasion." (PMID 28977889, 2017). "It is clear that further studies including high grade and advanced cancers and also focusing on E1S uptake transporters are needed to clarify the clinical performance of STS inhibitor." (PMID 28690541, 2017). "Therefore, it is not surprising that several experimental evidences have clearly pointed out the therapeutic utility of STS inhibitors in the treatment of hormone-dependant cancers." (PMID 40172115, 2025). "Similarly, several studies have shown the potential of STX140 as an anticancer agent as it targets steroid sulfatase and exhibits antiproliferative activities against a range of cancer cell lines and also inhibits angiogenesis." (PMID 36978428, 2023). "Several categories of drugs have been developed to treat these cancers, including estrogen-blocking drugs such as estrogen receptors (ERs) blockers and inhibitors of estrogen synthesis enzymes such as aromatase and steroid sulfatase (STS), with mixed results." (PMID 36311820, 2022). "STS is a crucial enzyme in the biosynthesis of active hormones (including oestrogens and androgens) and, therefore, represents an extremely attractive molecular target for the development of hormone-dependent cancer therapies." (PMID 32363947, 2020). "The results of some clinical trials dedicated to known STS inhibitors seem to be promising and such compounds have currently a great chance to be used in the treatment of several hormone-dependent types of cancer (especially, hormone-dependent breast cancer [HDBC])." (PMID 32363947, 2020). "Given that one of the main presumptive functions of STS is facilitating the supply of oestrogens to the carcinoma from otherwise unavailable circulating steroids, it is interesting to test if there is an interaction between endocrine manipulations and the survival benefit shown by STS expression." (PMID 29563635, 2018).
cancer (continued). "Interestingly, cancer cell migration, invasion, and MMPs expression induced by STS were also inhibited by a STS inhibitor." (PMID 28977889, 2017). "The situation in high grade cancers and especially advanced/recurrent cases may be different as suggested by decreased STS mRNA and protein levels seen in high grade vs. low grade cancers." (PMID 28690541, 2017). "Furthermore, STS inhibitors are also suitable as enzyme–based cancer imaging agents applied in the biomedical imaging technique positron emission tomography (PET) for cancer diagnosis." (PMID 23476785, 2013). "Furthermore, it highlighted the applicability of STS inhibitors to function as enzyme-based cancer imaging agents applied in the biomedical imaging technique positron emission tomography for the diagnosis and therapy of estrogen-sensitive cancers." (PMID 24251041, 2013). "Furthermore STS inhibitors might also be suitable as enzyme-based cancer imaging agents applied in the biomedical imaging technique positron emission tomography for the diagnosis and therapy of estrogen-sensitive cancer." (PMID 23476785, 2013). "Since STS was positively associated with CDC47 expression, it might be hypothesized that the overexpression of STS can lead to an increased estrogen-dependent proliferation of cancer." (PMID 21556246, 2009). "The biosynthesis of active steroids (e.g., estradiol (E2) and androstenediol (Adiol)) in cancer tissues mainly depends on three enzymatic pathways: aromatase (AROM), 17β-hydroxysteroid dehydrogenase (17β-HSD) and steroid sulfatase (STS)." (PMID 34279404, 2021). "High expression of STS and low expression of SULT1E1 will increase levels of active estrogens in malignant tumor cells leading to the stimulation of cell proliferation and cancer progression." (PMID 23476785, 2013). "To accomplish this, we developed specific antibodies against STS and EST1E1 that we used to analyze the expression of these enzymes in human carcinomas and adjacent normal breast tissues by immunohistochemical localization studies." (PMID 21556246, 2009). "Steroid sulfatase (STS) hydrolyzes estrone sulfate (E1S) and dehydroepiandrosterone sulfate (DHEAS) to their unconjugated biologically active forms, which modulate the growth and survival of estrogen-dependent cancers such as those of the prostate and breast." (PMID 28977889, 2017). "MCF7 cells increase STS activity in response to IL-6 and TNFα without alteration in STS mRNA levels, a trait also noted in other cancer cell lines." (PMID 26213785, 2015). "Immunohistochemical analyses have showed that STS expression is higher in carcinomas than in adjacent normal tissues (p = 0.064), although not to a significant level." (PMID 21556246, 2009). "Following cellular uptake by organic anion transporting polypeptides (OATP) or organic anion transporters (OAT), STS and SULT regulate the formation of active estrogens and androgens, thus disturbed balance between STS and SULT can contribute to the onset and progression of cancer." (PMID 38994718, 2024).
tumor (29 papers, 2009 to 2025). "Conversely, the expression of oestrogen sulfotransferase (EST), which opposes the actions of STS, inversely correlates with tumour size, lymph node status and is significantly associated with a decreased risk of recurrence and improved overall survival." (PMID 28612226, 2017). "For instance, the expression of STS, which is associated with higher availability of estrogens in tumor cells, can provide a growth advantage to CTC and its inhibition can be used to block such event and decrease the risk of recurrences." (PMID 25261936, 2014). "Compounds 16 and 18 have been shown to inhibit steroid sulfatase (STS), which is involved in increasing the free steroid levels in tumor cells." (PMID 39330376, 2024). "This is a strong inhibitor of steroid sulfatase and tubulin in addition to exhibiting antiproliferative activity against tumor cells at low concentrations." (PMID 36865913, 2023). "To date, more sulphamoylated derivatives of 2ME have been developed, including EM-191361 112, which shows to be a potent STS inhibitor able to block tumour growth (MCF-7 xenograft) in nude mice." (PMID 32363947, 2020). "It has been determined that EO-33 effectively inhibits STS activity by 81% in the liver and blocks 90% of tumour growth induced by oestradiol sulphate (E2S)." (PMID 32363947, 2020). "STS inhibitors showed promising results in a mouse subcutaneous model of EC, with decreased tumor growth by 48–67%." (PMID 30283331, 2018). "Although tumor STS activity was almost completely ablated by STX64 treatment, HCT116[vo] xenograft growth was not affected by STS inhibition." (PMID 28945888, 2017). "The stratification according to clinical and histopathological data confirmed the effects of tumor differentiation on STS expression." (PMID 28690541, 2017). "STS mRNA and activity are higher in many cancerous tissues compared to normal, implying an important role in hormone-dependent tumor growth (see Section VI)." (PMID 26213785, 2015). "Moreover, higher levels of STS inhibition weremeasured in the collected tissues (tumor and liver), suggesting amain role of STS inhibition as a mechanism of action of such a beneficialtherapeutic effect." (PMID 35235747, 2022). "Since no in vivo imaging studies were reported, it remains unclear whether the reported selectivity will result in increased tumor accumulation through reaction with STS, compared to remaining bound to the blood through reaction with CA." (PMID 28927325, 2017). "Furthermore, STS activity did not correlate with Dukes’ stage or T stage, indicating increased STS activity is most likely an early event in tumor formation." (PMID 28945888, 2017). "In the current study, we set out to test the hypothesis that inhibition of STS with irosustat for 2 weeks in patients with ER-positive breast cancer can result in a significant decrease in tumour proliferation as measured by FLT uptake and Ki67." (PMID 28795252, 2017). "Several studies reported that the expression of STS in tumor cells might imply the progression of the tumor and indicate a poor clinical outcome." (PMID 26240785, 2015). "Therefore, it may be effectively utilised as an STS inhibitor in the treatment of hormone-dependent cancers, however, due to its multitargeting activities, it may be considered in the treatment of tumours with hormone-independent nature as well." (PMID 32363947, 2020). "However, moderate to strong expression of STS was observed in only 37 and 25% of the primary and recurrent cases, and the preponderance of tumours with low STS expression clearly may have impacted on the efficacy data." (PMID 28612226, 2017). "Several enzymes related to androgen biosynthesis and (re-)activation were highly expressed in all tumor biopsy samples, including HSD17B10, STS, SRD5A1, AKR1C3, and HSD11B2." (PMID 33974560, 2021). "Similar to OATPs, STS has become an active target for inhibitor synthesis, in an attempt to prevent circulating DHEAS from contributing to tumor growth." (PMID 35582271, 2019).
tumor (continued). "Of these, 8 genes showed a significant decrease in expression in tumor samples with this deletion relative to tumors samples without this deletion: ARSD, ARSE, MXRA5, PRKX, LOC729137, NLGN4X, HDHD1A, and STS." (PMID 19419571, 2009). "Immunofluorescence and immunohistochemistry reactions showed that steroid sulfatase (STS) was located in the cytoplasm of epithelial tumor cells displaying a distribution similar to cytokeratins, whereas the androgen receptor (AR) was identified in the nucleus of tumor epithelium." (PMID 34321053, 2021).
infection (11 papers, 2010 to 2022). The state of being infected such as from the introduction of a foreign agent such as serum, vaccine, antigenic substance or organism. "Unlike T. friulano, in the present study the susceptible variety showed wider defense response to FD infection at 6 dpi, mostly related to an increase in expression of several STS genes and several genes with high homology to plant laccases, as confirmed in the co-expression analyses." (PMID 31242866, 2019). "The genes commonly associated with this pathway (PR10.3, STS, STS8, Vv17.3) were also up-regulated early in the kinetics, indicating that a rapid signal occurs (i.e., within hours of infection) in grapevine woody tissue." (PMID 27014294, 2016). "Genes encoding enzymes involved in the biosynthesis of antimicrobial phytoalexins (PAL, STS) and in detoxification (GST1) were more up-regulated upon infection with Np-Bt67 and Np-B than NpB-UV9 (1.3 to 2.7-fold)." (PMID 35330321, 2022). "However, only slight differences were observed regarding transcript levels of LOX9, GST1, and STS, while the expression levels of PR1, PR3, PR4, and PR10 did not change in bacteria-treated plants compared to control after pathogen infection." (PMID 30733727, 2019).
neurodevelopmental disorder (2 papers, 2011 to 2018). A behavioral and cognitive disorder with onset during the developmental period that involves impaired or aberrant development of intellectual, motor, or social functions. "Deletions encompassing the X-linked STS gene (encoding steroid sulfatase) have been observed in subjects with neurodevelopmental disorders, including attention deficit hyperactivity disorder (ADHD)." (PMID 21255266, 2011).
genodermatosis (1 paper, 2022). "X-linked recessive ichthyosis (XLI) is a genodermatosis, caused by a deficiency of the steroid sulphatase enzyme encoded by the STS gene (OMIM # 300,747)." (PMID 35883075, 2022).
gynecological diseases (1 paper, 2016). "The published data imply that inhibitors of STS have the potential for treatment of individual gynecological diseases." (PMID 26924986, 2016).
neurodegenerative disease (1 paper, 2022). A disorder of the central nervous system characterized by gradual and progressive loss of neural tissue and neurologic function. "Intriguingly, work in such models has shown that deletion of the STS orthologue, or inhibition of the STS enzyme, can actually enhance aspects of memory, alter hippocampal neurochemistry, protect against neurodegenerative disease‐associated pathology, and increase longevity." (PMID 36479267, 2022).